MAP4K4 (mitogen-activated protein kinase kinase kinase kinase 4)
Diseases named in the same sentence as MAP4K4 in open-access papers (continued):
Sharing a sentence is not in itself a finding about the gene and the disease.
atherosclerosis (9 papers, 2015 to 2025). A disease characterized by the build-up of fatty material and calcium deposition in the arterial wall resulting in partial or complete occlusion of the arterial lumen. "Importantly, the atherosclerosis protection in these animals was observed even with only a partial loss of endothelial Map4k4 expression." (PMID 26688060, 2015). "Thus, loss of MAP4K4 expression or activity in macrophages using genetic deletion strategies or via PF-06260933 treatment, respectively, could also ameliorate atherosclerosis." (PMID 26688060, 2015). "The overexpression of MYDGF in bone marrow attenuates leukocyte influx into the aorta and prevents atherosclerosis onset via the downregulation of PKCδ/MAP4K4/NF-κB signaling." (PMID 40427505, 2025). "MAP4K4 promotes endothelial permeability, enhancing the inflammatory response to lipid-mediated vascular damage leading to atherosclerosis." (PMID 37190200, 2023). "Constitutive silencing of endothelial MAP4K4 or inducible endothelial-specific MAP4K4 deletion ameliorated atherosclerosis development in mice as measured by histology of the aortic root and Oil Red-O staining of the aorta." (PMID 26688060, 2015). "In this study, we observed that MAP4K4 expression and/or activity was increased in the aortas of mice and humans with atherosclerosis." (PMID 26688060, 2015). "The significant reduction in atherosclerosis that was observed in MAP4K4-depleted mice suggested that endothelial MAP4K4 was a potent regulator of vascular inflammation." (PMID 26688060, 2015). "Taken together, these results reveal that MAP4K4 is a key signalling node that promotes immune cell recruitment in atherosclerosis." (PMID 26688060, 2015). "Recent reports additionally suggest that endothelial MAP4K4 enhances endothelial permeability, which can promote inflammation and atherosclerosis progression." (PMID 26688060, 2015). "Sweroside alleviated endothelial injury and atherosclerosis through MAP4K4/NF‐κB signalling." (PMID 40913245, 2025). "Bone marrow transplantation or bone marrow-specific overexpression of MYDGF attenuated leukocyte homing in the aortas of atherosclerotic mice and ameliorated atherosclerosis by reducing inflammation and endothelial cell damage via the PKCδ/MAP4K4/NF-κB pathway." (PMID 39030488, 2024). "Furthermore, the results we present with specific MAP4K4 kinase inhibitor PF-06260933 reveals that MAP4K4 is a novel and important anti-atherosclerosis therapeutic target." (PMID 26688060, 2015). "Thus, the data presented here indicate a central role for MAP4K4 in promoting vascular inflammation and atherosclerosis." (PMID 26688060, 2015). "We hypothesized that the protection from atherosclerosis observed in MAP4K4 ECKO and MAP4K4 KD animals was due to impaired leukocyte recruitment through the EC barrier and accumulation within the atherosclerotic plaque." (PMID 26688060, 2015). "MAP4K4 silencing in cultured ECs attenuates cell surface adhesion molecule expression while reducing nuclear localization and activity of NFκB, which is critical for promoting EC activation and atherosclerosis." (PMID 26688060, 2015). "Therefore, while MAP4K4 likely has actions in multiple cell types to promote atherosclerosis in mice, protection from and treatment of atherosclerosis by PF-06260933 is consistent with endothelial MAP4K4 as one of multiple targets for the action of PF-06260933 to mediate these beneficial effects." (PMID 26688060, 2015). "Genetic tissue-specific deletions of MAP4K4 in macrophages as well as smooth muscle on the Apoe−/− background will be performed in the future to assess the contribution of these tissues to the overall atherosclerosis protection observed after PF-06260933 treatment." (PMID 26688060, 2015). "MYDGF inhibits MAP4K4 phosphorylation and decreases FOXO3a signaling and LDL transcytosis, rendering protection against atherosclerosis onset." (PMID 40427505, 2025).
atherosclerosis (continued). "On the basis of the protection observed in development of atherosclerosis after MAP4K4 depletion in genetic mouse models, we attempted to verify these results and determine whether inhibiting the protein kinase activity of MAP4K4 would also protect against atherosclerosis development." (PMID 26688060, 2015). "In atherosclerotic plaques, there was a significant 3.8-fold increase in MAP4K4 mRNA expression compared with coronary or aortic arterial samples from human subjects who did not have atherosclerosis." (PMID 26688060, 2015). "However, the role of endothelial MAP4K4 in models of in vivo chronic inflammatory processes such as atherosclerosis has not yet been assessed." (PMID 26688060, 2015).
gastric cancer (9 papers, 2019 to 2025). A primary or metastatic malignant neoplasm involving the stomach. "In addition to its association with prognosis, MAP4K4 expression has been linked to other clinical features in gastric cancer." (PMID 39941781, 2025). "The overexpression of MAP4K4 was associated with gastric cancer’s invasion, progression, and metastasis, suggesting that MAP4K4 could serve as a prognostic marker for gastric cancer." (PMID 37190200, 2023). "Moreover, the group with a higher MAP4K4 expression presented a higher risk, indicating that MAP4K4 is a risk factor in gastric cancer." (PMID 36292671, 2022). "This study identifies the high expression of MAP4K4 as a biomarker of poor prognosis in microsatellite instability gastric cancer." (PMID 39941781, 2025). "Sanguinarine inhibits the proliferation of BGC-823 gastric cancer cells by downregulating the expression of miR-96-5p and miR-29c-3p and upregulating the expression of MAP4K4, pMEK4, and pJNK1 protein in gastric cancer cells BGC-823." (PMID 37764364, 2023). "In the present study, we comprehensively analyzed the expression and regulatory mechanisms of MAP4K4 based on the gastric cancer public dataset obtained from TCGA." (PMID 36292671, 2022). "Although this study analyzed the role of MAP4K4 in gastric cancer, extensive research is needed to further evaluate the specific mechanism of MAP4K4 promoting the occurrence of gastric cancer." (PMID 36292671, 2022). "To validate the cancer-promoting role of MAP4K4 in gastric cancer, we first detected the differences in MAP4K4 expressions in tumor and adjacent samples." (PMID 36292671, 2022). "In conclusion, MAP4K4 was identified as one of the overexpressed molecules in gastric cancer tissues and was closely related to the progression, invasion, and metastasis of gastric cancer." (PMID 36292671, 2022). "The obtained results provide a better understanding of the role of MAP4K4 in gastric cancer progression and a potential therapeutic target and prognostic predictor against this malignancy." (PMID 36292671, 2022). "Meanwhile, the expression of MAP4K4 was determined by qPCR in gastric cancer cell lines (MGC-803, MKN-28, SGC-7901, and OCUM-1) and control cells (human gastric mucosa epithelial cell GES-1 cell line)." (PMID 36292671, 2022). "MAP4K4 is highly expressed in gastric cancer, predicting a poor prognosis and promoting gastric cancer invasion and metastasis." (PMID 36292671, 2022). "Although there are some reports on the role of MAP4K4 in gastric cancer, complete and comprehensive bioinformatics and experimental analyses are still required to explore the entire role of MAP4K4." (PMID 36292671, 2022). "Collectively, our findings reveal that MAP4K4 plays a crucial role in the progression of gastric cancer." (PMID 36292671, 2022). "Additionally, proteins identified via Grape-Pi in gastric samples demonstrated a high correlation with mRNA data and identified gastric cancer proteins, like MAP4K4, missed by conventional methods." (PMID 40406669, 2025). "Interestingly, MAP4K4 expression has been previously studied in gastric cancer, demonstrating its prognostic predictive ability." (PMID 39941781, 2025). "Furthermore, MAP4K4 inhibition provoked tumor cell apoptosis (by increasing the Bax/Bcl-2 ratio) and inhibited tumor cell proliferation in a gastric cancer model." (PMID 37223681, 2023). "MAP4K4 high expression negatively impacts the prognosis of gastric cancer patients, suggesting that MAP4K4 should be regarded as an important prognostic factor for gastric cancer." (PMID 36292671, 2022). "This suggests MAP4K4 as an important prognostic factor for gastric cancer and could be regarded as a new potential prognostic detection and therapeutic target." (PMID 36292671, 2022).
gastric cancer (continued). "TCGA analysis revealed that MAP4K4 expression in the tumor was significantly higher than in the adjacent samples, indicating that MAP4K4 might be a tumor-promoting gene in gastric cancer, which was consistent with the previous reports on cancers." (PMID 36292671, 2022). "Finally, we confirm the high expression of MAP4K4 in gastric cancer and its possible carcinogenic effect." (PMID 36292671, 2022). "Further attention should be paid to the abnormality of MAP4K4 in the progression of gastric cancer." (PMID 36292671, 2022). "In addition, we also compare and analyze the immune microenvironment of MAP4K4 groupings in gastric cancer, and the results show that some immune scores are positively correlated with MAP4K4." (PMID 36292671, 2022). "The miR-582-3p/miR-141-3p/miR-181c-5p and MAP4K4 signaling mechanisms might also play a role in gastric cancer." (PMID 36292671, 2022). "The overall analyses revealed MAP4K4 as a new and reliable potential marker that could predict the prognosis of gastric cancer." (PMID 36292671, 2022). "Therefore, this study aims to determine the tumor-promoting role of MAP4K4 in gastric cancer and whether it can be used as a new and reliable biomarker to predict the prognosis of gastric cancer." (PMID 36292671, 2022). "The expression of MAP4K4 in tumor samples was significantly higher than in normal samples (p-value 4.4 × 10−107), suggesting that MAP4K4 might play an oncogenic role in gastric cancer." (PMID 36292671, 2022). "However, our study suggests that the prognostic value of MAP4K4 may not be applicable to all molecular subtypes of gastric cancer, with MSI-GC tumors being a suitable group for this biomarker." (PMID 39941781, 2025).
medulloblastoma (9 papers, 2015 to 2025). A malignant, invasive embryonal neoplasm arising from the cerebellum. "However, depletion of either STRN3 or MAP4K4 in medulloblastoma cells reduces invasion, and loss of both proteins abrogates tumor cell growth in the cerebellar tissue." (PMID 35941177, 2022). "Herein we addressed the expression, subcellular localization, and function of CLSTN1 in the embryonal brain tumor medulloblastoma and further explored its previously observed regulation by the pro-invasive kinase MAP4K4." (PMID 39762313, 2025). "In medulloblastoma tumor cells, Map4k4 enhances endocytic activity and the depletion of Map4k4 impairs hepatocyte growth factor-induced dextran endocytosis." (PMID 37508356, 2023). "Spatial proteomics identifies MAP4K4 as a regulator of the plasma membrane-associated proteome and reveals CD155 and EndoA1 as mediators of proliferation and invasiveness in medulloblastoma cells." (PMID 35296518, 2022). "In medulloblastoma, the MAP4K4-STRIPAK complex interaction promotes growth factor-induced phosphorylation of PKCθ on T538 and this activation of PKCθ is necessary for tumor cell invasion." (PMID 36568222, 2022). "In adult patient-derived glioma cells, MAP4K4 is necessary for pro-metastatic functions, and in pediatric medulloblastoma cells, it promotes invasion induced by epidermal (EGF), hepatocyte (HGF) and basic fibroblast growth factor (bFGF)." (PMID 36568222, 2022). "In an in vitro model of medulloblastoma, MAP4K4 interacted with STRN3/4 and stimulated cell growth." (PMID 37223681, 2023). "Thus, STRN3 is a master regulator of MAP4K4 function, and disruption of its cooperation with MAP4K4 reactivates Hippo signaling and represses tissue invasion in medulloblastoma." (PMID 35941177, 2022). "Finally, targeting MAP4K4 controlled endocytic activity could represent a novel druggable vulnerability in medulloblastoma cells to restrict tumor growth and dissemination." (PMID 35296518, 2022). "The cooperation of MAP4K4 and STRN3 in the STRIPAK complex promotes a pro-migratory and invasive phenotype in medulloblastoma cells through the activation of downstream effector PKCθ." (PMID 36568222, 2022). "determined the MAP4K4 interactome in HEK293T cells and in the medulloblastoma cell line DAOY." (PMID 36568222, 2022). "Recently, MAP4K4 expression was shown to be increased in 30% of primary medulloblastoma tumors, particularly in the metastatic SHH β subtype, and was shown to promote the migratory and invasive behavior of medulloblastoma tumor cells." (PMID 31570734, 2019).
cervical cancer (8 papers, 2021 to 2024). A primary or metastatic malignant neoplasm involving the cervix. "MAP4K4 also reduced the chemosensitivity of cervical cancer cells to platinum therapy by regulating SOX6-induced autophagy." (PMID 37223681, 2023). "More importantly, this study sheds new light on the usage of MAP4K4 inhibitors to increase the sensitivity of cervical cancer cells to platinum-based chemotherapy." (PMID 40396003, 2022). "Consistent with a potential implication of MAP4K4 in sensitization of tumor cells to chemotherapy, MAP4K4 was recently found to reduce the sensitivity of cervical cancer cells to cisplatin treatment via an autophagy-controlled mechanism." (PMID 35296518, 2022). "More importantly, this study shed new light on the usage of MAP4K4 inhibitors to increase the sensitivity of cervical cancer cells to the platinum-based chemotherapy." (PMID 34930918, 2021). "The results revealed that the levels of SOX6 protein and its downstream MAP4K4 protein in the frozen cervical cancer tissues of patients who were sensitive to cisplatin were lower than those in patients who were not sensitive to cisplatin." (PMID 34930918, 2021). "Additionally, the use of RNA interference (miR-200c) to block MAP4K4 in cervical cancer diminished the invasive behavior of the cancer cells in vitro." (PMID 37223681, 2023). "miR-200c inhibited the metastasis and growth of cervical cancer cells via targeting MAP4K4." (PMID 35154284, 2022). "In this study, we found that SOX6 could induce autophagy in cervical cancer cells, and mitogen-activated protein kinase kinase kinase kinase-4 (MAP4K4) gene was identified as a direct target gene of SOX6." (PMID 34930918, 2021). "Moreover, cisplatin itself could promote the expression of endogenous SOX6 and subsequently the MAP4K4-mediated autophagy in cervical cancer cells, which might in turn reduce the sensitivity of these cells to cisplatin treatment." (PMID 34930918, 2021). "Based on the phenomenon that the SOX6-induced autophagy mediated by MAP4K4 could reduce the sensitivity of cervical cancer cells to cisplatin treatment, we further investigated whether the sensitivity to cisplatin could be increased by inhibiting autophagy or MAP4K4 expression." (PMID 34930918, 2021). "MAP4K4 and WT1 contribute to SOX6‐induced cellular senescence in cervical cancer by synergistically activating the ATF2–TGFβ2–Smad2/3 signaling pathway." (PMID 38383842, 2024). "In summary, this study found that MAP4K4 and WT1 contributed to SOX6‐induced cellular senescence in cervical cancer by synergistically activating the ATF2–TGFβ2–Smad2/3 signaling pathway." (PMID 38383842, 2024). "This study uncovers that the MAP4K4/WT1–ATF2–TGFβ2 axis mediates SOX6‐induced cellular senescence, which is a promising therapeutic target in improving the chemosensitivity of cervical cancer." (PMID 38383842, 2024). "Mitogen-activated protein kinase kinase kinase kinase-4 (MAP4K4) was responsible for mediating the SOX6-induced autophagy, resulting in reduced chemosensitivity in cervical cancer." (PMID 38062424, 2023). "In this study, we firstly found that SOX6-induced autophagy of cervical cancer cells depending on its HMG domain, and MAP4K4 gene was identified as the potential target gene of SOX6 through microarray and RNA-sequencing analyses." (PMID 34930918, 2021). "Because MAP4K4 is upstream in the pathway mediating SOX6-induced autophagy, so its inhibitor may be more specific in increasing the sensitivity of cervical cancer cells to cisplatin chemotherapy." (PMID 40396003, 2022). "In turn, we found that both the level of endogenous SOX6 protein and its induced autophagy are significantly increased under cisplatin treatment, and accompanied by an increased level of MAP4K4, activation of the MAPK/ERK pathway, and inhibition of the PI3K-AKT-MTOR pathway in cervical cancer cells." (PMID 40396003, 2022).
cervical cancer (continued). "Taken together, the sensitivity of cervical cancer cells to cisplatin could be increased by inhibiting the SOX6-induced autophagy through both autophagy and MAP4K4 inhibitors." (PMID 34930918, 2021). "Taken together, these results suggested that the sensitivity of cervical cancer cells to cisplatin could be increased by inhibiting SOX6-induced autophagy through both autophagy and MAP4K4 inhibitors." (PMID 34930918, 2021). "Moreover, the sensitivity of cervical cancer cells to cisplatin could be increased by inhibiting SOX6-induced autophagy through both autophagy and MAP4K4 inhibitors." (PMID 34930918, 2021). "Further, the sensitivity of cervical cancer cells to cisplatin chemotherapy could be reduced by the SOX6-induced autophagy in vitro and in vivo, while such a phenomenon could be turned over by autophagy-specific inhibitor and MAP4K4 inhibitor, respectively." (PMID 34930918, 2021). "Since MAP4K4 was at the upstream of SOX6-induced autophagy, its inhibitor might be more specific in inhibiting autophagy and subsequently increasing the sensitivity of cervical cancer cells to cisplatin chemotherapy." (PMID 34930918, 2021). "In this study, we further found that MAP4K4 could mediate the SOX6-induced autophagy through inhibiting PI3K-Akt-mTOR pathway and activating MAPK/ERK pathway, which could reduce the sensitivity of cervical cancer cells to cisplatin chemotherapy in vitro and in vivo." (PMID 34930918, 2021).